LHX6 (LIM homeobox 6)
Diseases named in the same sentence as LHX6 in open-access papers:
LHX6 is named in the same sentence as 42 diseases in open-access papers, as found by Europe PMC text mining. Sharing a sentence is not in itself a finding about the gene and the disease. The quoted sentences say what the papers report.
cervical cancer (7 papers, 2017 to 2025). A primary or metastatic malignant neoplasm involving the cervix. "In this work, we evaluated the expression patterns and potential roles of different LHX6 isoforms in cervical cancer." (PMID 35384355, 2022). "As our analysis indicated that LHX6EX(+12) group was the major oncogenic subtype of LHX6 in cervical cancer, hence bioinformatics analysis was proceeded for the Sh‐LHX6EX(+12) & Sh‐LHX6All group." (PMID 35384355, 2022). "To better understand the transcriptional regulatory mechanism of the LHX6 isoforms in cervical cancer, we performed RNA‐seq in the Sh‐LHX6EX(−12), Sh‐LHX6EX(+12), Sh‐LHX6All knockdown group, and their control of HeLa cells, respectively." (PMID 35384355, 2022). "We detected, for the first time, the mRNA expression level of two different LHX6 isoform groups in cervical cancer and normal cervical samples by qRT‐PCR, and analyzed their clinical significance." (PMID 35384355, 2022). "The relative mRNA quantity of LHX6EX(+12) group was higher than that of the LHX6EX(−12) group in cancer tissues (p = 0.0147), indicating that the LHX6EX(+12) group was the dominant component of LHX6 in cervical cancer." (PMID 35384355, 2022). "In summary, our work described, for the first time, the expression patterns and biological roles of two different LHX6 isoform groups in cervical cancer." (PMID 35384355, 2022). "Additionally, LHX6-NDUFA8 was more recurrent than other previously reported fusions in cervical cancer." (PMID 36527429, 2023). "More importantly, our results indicated that LHX6EX(+12) isoform group was the dominant constituent and oncogenic type of LHX6 in cervical cancer, supporting its potentials as a new biomarker and a precise therapeutic target for cervical cancer in the future by managing the oncogenic LHX6 isoforms." (PMID 35384355, 2022). "Moreover, as the LHX6EX(+12) isoform group was the dominant composition of LHX6, we proposed that LHX6 promoted cervical cancer cell growth mainly through the function of the LHX6EX(+12) group." (PMID 35384355, 2022). "Hence, this study aimed to investigate the precise expression patterns and biological functions of different LHX6 isoforms in cervical cancer, expecting to find a new biomarker and therapeutic target for it." (PMID 35384355, 2022). "In summary, our study indicated that LHX6EX(+12) isoform group was the key constituent of LHX6 in the promotion of cervical cancer cell growth, and thus may be a new biomarker and a precise therapeutic target for cervical cancer in the future." (PMID 35384355, 2022). "And LHX6EX(+12) isoform group was the predominant oncogenic subtype of LHX6 in cervical cancer, which could be a new biomarker and a potential precise therapeutic target for cervical cancer in the future." (PMID 35384355, 2022). "However, we found that few studies had reported the expression patterns and biological roles of different LHX6 isoforms in cervical cancer." (PMID 35384355, 2022). "The results may be due to the limitation of sample size in our study, and the differential expression of the two LHX6 subtype groups may also occur in cervical cancer patients of specific subtypes or clinicopathological parameters that we do not know yet." (PMID 35384355, 2022). "In summary, our results indicated that LHX6EX(+12) isoform group was the dominant oncogenic type of LHX6 in cervical cancer, which may be a new biomarker and a potential precise therapeutic target for cervical cancer in the future." (PMID 35384355, 2022). "Importantly, the LHX6EX(+12) isoform group may play a dominant role in the cancer‐promoting effects of LHX6 in cervical cancer." (PMID 35384355, 2022). "Interestingly, 53 out of 56 co‐regulated genes exhibited the same regulatory potential (either upregulated or downregulated), supporting our hypothesis that the LHX6EX(+12) group might be the key component of LHX6 in the promotion of cervical cancer cell growth." (PMID 35384355, 2022).
cervical cancer (continued). "However, the expression patterns of different LHX6 isoforms in cervical cancer are unknown." (PMID 35384355, 2022). "The cis-SAGe LHX6-NDUFA8 was determined in cervical cancer cells, with no detectable expression in normal cells." (PMID 41155268, 2025). "Two isoforms of the cis-SAGe LHX6-NDUFA8 were detected exclusively in cervical cancer tissues and Pap smears and not in normal controls." (PMID 36527429, 2023). "To further explore the biological roles of two LHX6 isoform groups, knockdown and regain of functional experiments were conducted and we identified differences in the biological roles of the LHX6EX(+12) isoform group and LHX6EX(−12) group in cervical cancer cells." (PMID 35384355, 2022). "Previously, we identified a highly frequent (>10%) chimeric RNA named LHX6‐NDUFA8 which was detected exclusively in cervical cancer tissues and Pap smears, but not in normal cervical tissues, supporting its potential as an early molecular biomarker for cervical cancer." (PMID 35384355, 2022). "However, the specific molecular mechanism of LHX6 exon 12 in promoting cervical cancer growth was not clearly described due to the limitation of our study." (PMID 35384355, 2022).
breast carcinoma (6 papers, 2017 to 2026). "LHX6 is associated with many kinds of cancers and can inhibit the proliferation, invasion, and migration of breast cancer cells by modulating the PI3K/Akt/mTOR and Wnt/β-catenin signaling pathways." (PMID 35203526, 2022). "LHX6 inhibits cell proliferation and invasion when overexpressed in breast cancer cells." (PMID 31810245, 2019). "Previous studies have found that LHX6 modulated the carcinogenicity of breast cancer cells via β-catenin/TCF4 complex, we thus speculated that LHX9 might have the similar regulatory function on OS through β-catenin/TCF4 since it was the homologue of LHX6." (PMID 31788020, 2019).
lung carcinoma (6 papers, 2016 to 2024). "For instance, in lung we found FOXA2, TBX4 and BMP4, and although the role of LHX6 in lung development is less well defined, it has previously been implicated as a tumour suppressor in lung cancer." (PMID 27562343, 2016). "Previous study indicates that LHX6 is a candidate tumor suppressor gene that has epigenetic silencing in patients with lung cancer." (PMID 27610375, 2016). "This suggests that LHX6 may be a novel target for improving drug resistance in anticancer studies, along with a previous study that showed that down-regulation of LHX6 can induce resistance to chemotherapy in lung cancer." (PMID 31810245, 2019). "Moreover, hypermethylation of LHX6 is not found in normal lung tissues; however, it is observed in more than 50% of primary lung cancer." (PMID 31810245, 2019).
hepatocellular carcinoma (4 papers, 2020 to 2025). A malignant tumor that arises from hepatocytes. "sEVs derived from hypoxic hepatocellular carcinoma cells deliver miR-1273f, which increases proliferation and metastasis by targeting LIM Homeobox 6 (LHX6), an inhibitor of the Wnt/β-catenin pathway." (PMID 32709110, 2020).
cleft palate (3 papers, 2006 to 2024). Cleft palate is a fissure type embryopathy that affects the soft and hard palate to varying degrees. "Nevertheless, the precise role and underlying mechanism of Lhx6 in the pathogenesis of cleft palate remain incompletely understood." (PMID 39438838, 2024). "As a promising molecular marker, the deficiency of Lhx6 could potentially elevate the risk of cleft palate occurrence, and genetic screening for Lhx6 and its related biomarkers may play a contributive role in the prevention of such malformations." (PMID 39438838, 2024). "This research pioneers the discovery of Lhx6’s role in mediating mitophagy associated with the development of cleft palate, offering novel insights into the etiology of malformations and highlighting the application value of molecular research in the screening of developmental malformations." (PMID 39438838, 2024). "The LIM-homeodomain transcription factors LHX7 and LHX6 have been implicated in palatogenesis in mice and thus may also contribute to the incidence of isolated palatal clefts and/or clefts of the lip and primary palate (CL/P) in humans." (PMID 16563169, 2006). "In conclusion, RA has been found to induce dysfunction in HEPM cell proliferation and migration, leading to the development of cleft palate through the downregulation of Lhx6 and subsequent mitochondrial dysfunction." (PMID 39438838, 2024). "Our research underscores the significance of Lhx6 in developmental processes and proposes the restoration of Lhx6 as a potential therapeutic strategy for the prevention of cleft palates." (PMID 39438838, 2024). "The importance of Lhx6/8 in palatal development has also been recognized, but the role of Lhx6 in cleft palate and its specific mechanisms have not been studied in depth by our group, and only a small number of studies have reported the role of the Lhx6 gene in cleft palate development." (PMID 39438838, 2024).
Tourette syndrome (3 papers, 2020 to 2025). A neurologic disorder caused by defective metabolism of the neurotransmitters in the brain. "The orthologue of Awh, lhx6, has emerged as a probable candidate for Tourette syndrome, a neuro-muscular disease." (PMID 40300650, 2025). "In conclusion, we identified a positive association between rs1042201 in AADAC gene and a significant association between rs3750486 in the LHX6 and rs7795011 in the IMMP2L genes with Tourette Syndrome, thus providing support for their possible biological role in the etiology of the disorder." (PMID 32922348, 2020). "Moreover, a decrease in both GABAergic and cholinergic interneurons in the ventral telencephalon has been reported in Tourette Syndrome, suggesting LHX6 and LHX8 correlation with Tourette Syndrome due to their role in GABAergic and cholinergic interneuron specification in the striatum." (PMID 35546872, 2022).
gastric cancer (2 papers, 2019 to 2023). A primary or metastatic malignant neoplasm involving the stomach. "In gastric cancer, the inhibition of miR-214 up-regulates LHX6 and improves resistance to erlotinib." (PMID 31810245, 2019).
liver cancer (2 papers, 2021 to 2022). An epithelial or non-epithelial malignant neoplasm that arises from the liver.
non-small cell lung carcinoma (2 papers, 2017 to 2025). A group of at least three distinct histological types of lung cancer, including non-small cell squamous cell carcinoma, adenocarcinoma, and large cell carcinoma. "A concrete example of this can be observed in the capacity to modify the resistance to erlotinib in the non-small cell lung cancer (NSCLC) HCC827 cell line through the decrease of miR-214 expression and its subsequent target LHX6." (PMID 40521034, 2025).
schizophrenia (2 papers, 2012 to 2020). A major psychotic disorder characterized by abnormalities in the perception or expression of reality. "Further, many of the genetic cascades downstream of Lhx6 have also been implicated in schizophrenia." (PMID 32497066, 2020). "We recently reported decreased LHX6 mRNA levels in the PFC of subjects with schizophrenia." (PMID 22937123, 2012). "Taken together, we posit that the decrease in Dlx1, Dlx5, and Lhx6 expression that we observed in our schizophrenia models may lead to the cell-specific deficits in interneuron development that are thought to play a key role in the pathophysiology of schizophrenia." (PMID 32497066, 2020). "Identifying genes that are regulated by LHX6 may help inform molecular mechanisms of the alterations in PV and SST neurons in schizophrenia." (PMID 22937123, 2012). "KCNS3 and LHX6 might be useful for characterizing cell-type specific molecular alterations of cortical GABA neurotransmission and for the development of novel treatments targeting PV and/or SST neurons in schizophrenia." (PMID 22937123, 2012). "Interestingly, a subset of schizophrenia subjects was identified by the presence of consistent deficits in LHX6, GAD67, PV and SST mRNAs, suggesting that LHX6 deficits may affect development and/or maintenance of GABAergic phenotype in PV and SST neurons in these subjects." (PMID 22937123, 2012).
Anxiety (1 paper, 2022). Intense feelings of nervousness, tension, or panic often arise in response to interpersonal stresses. "First, to control for possible effects of Lhx6 knock-down on anxiety and locomotion, we exposed the animals to an open field arena and quantified the time spent in the center of the maze." (PMID 35318414, 2022).
Chagas disease (1 paper, 2022). A parasitic infection caused by Trypanosoma cruzi. "All those genes are involved in biological process associated to Chagas disease: nervous system (LHX6, POU6F2, MDGA1, DISC1, PCSK9), immune system (ZMIZ, HLA-DRB1), Wnt pathway (DISC1), ion transport (KCNK15, PCSK9), striated muscles (SMYD3) or ATP metabolic process (ATP5S)." (PMID 36248819, 2022).
Cognitive impairment (1 paper, 2019). Abnormal cognition is characterized by deficits in thinking, reasoning, or remembering. "It would be interesting to determine whether restricted ablation of Nkx2-1 and Lhx6 in MGE neuroprogenitors, which cause seizure phenotypes and abnormal electroencephalographic activity, also leads to cognitive impairments similar to the ones observed here for Nkx2.1-CBPKO mice." (PMID 30334186, 2019).
diabetes (1 paper, 2024). "In addition, decreased expression of Lhx6 has been reported in diabetes, tumors, and inflammatory environments, and Lhx6 is also involved in signaling pathways that regulate disease progression and regression, including p38, NF-κB and Wnt/β-catenin." (PMID 39438838, 2024).
epilepsy (1 paper, 2025). A brain disorder characterized by episodes of abnormally increased neuronal discharge resulting in transient episodes of sensory or motor neurological dysfunction, or psychic dysfunction. "Based on our results, we propose that the loss of LHX6 neurons in the GPe leads to reduced inhibitory control in the STN, contributing to the propagation of epilepsy in Ndufs4-cKO mice." (PMID 41321311, 2025).
neuritis (1 paper, 2018). A neuropathy arising from inflammation of one or more nerves. "Notably, the human PV+ neurons, which are induced by LHX6, pursued a multipolar structure with multiple neuritis beginning from the cell body (102 of 369 PV+ neurons)." (PMID 30251953, 2018).
neuroblastoma (1 paper, 2015). Neuroblastoma (NB) is the most common solid, extracranial childhood tumor. "We have uncovered that LHX6 also plays a role in cholinergic cell fate determination in C. elegans or human neuroblastoma cells and acts as a terminal selector to control the differentiation of neuronal subtypes." (PMID 26305787, 2015). "Furthermore, expression of either LHX6 or lim-4 is sufficient to drive cholinergic differentiation in human neuroblastoma cells." (PMID 26305787, 2015). "Thus, we tested whether overexpression of human LHX6 or C. elegans LIM-4 could promote expression of cholinergic markers in human neuroblastoma SH-SY5Ycells." (PMID 26305787, 2015).
orofacial cleft (1 paper, 2006). A disorder of facial skeleton that is characterized by cleft lip and/or cleft palate that result in feeding, speech and hearing problems caused by failures during development. "The manipulability, minimal cost and susceptibility of chicks to CL/P will enable more detailed investigations into how perturbations of IRF6, LHX6 and LHX7 contribute to common orofacial clefts." (PMID 16563169, 2006).
pancreatic cancer (1 paper, 2025). "Silencing LHX6 in pancreatic cancer enhances proliferation, likely through TFPI2 regulation." (PMID 40361374, 2025).
tooth agenesis (1 paper, 2016). A tooth disease characterized by failure to develop one or more missing teeth. "Consistently, the dental mesenchyme-specific transcription factors (Msx1, Pax9, and Lhx6) were decreased in cultured mDMCs, and the mutation of these transcription factors was shown to cause tooth agenesis disorders." (PMID 26925321, 2016).
tumor (14 papers, 2016 to 2025). "Several previous studies have demonstrated that LHX6 can inhibit the progression of multiple tumor types, including glioma, lung cancer, and breast cancer." (PMID 37046749, 2023). "LHX6 regulates Wnt/β-catenin signaling by inhibiting β-catenin expression, thereby inhibiting tumor progression." (PMID 37046749, 2023). "Epigenetic reduction of Lhx6 is related to cell proliferation and tumor formation in glia cells, hepatocytes and epithelial cells of the lung, suggesting that Lhx6 is required to maintain cellular differentiation in non-neuronal tissues." (PMID 35318414, 2022). "Previous studies have shown that LHX6 can play a tumor inhibitory role by inhibiting the downstream genes related to cell proliferation, cell migration, and metastasis." (PMID 35847938, 2022). "On the one hand, miR-214-3p increased the resistance to erlotinib and stimulated tumor proliferation and invasion by targeting LHX6 in patients with LADC43." (PMID 31492847, 2019). "It was consistent that oncogenic miR-21 and miR-155 involved in the progression and invasion of GBM, and a set of their common key targets such as LHX6, DRD1, NEUROG1 and RAB27B were also associated with tumor progression." (PMID 29312626, 2017). "Furthermore, LIM homeobox domain 6 (LHX6) suppresses Wnt/β-catenin signaling and upregulates TFPI2 through transcription factors like paired-like homeodomain transcription factor 2 (PITX2), contributing to tumor suppression and reduced cancer cell growth." (PMID 40361374, 2025).
cancer (8 papers, 2017 to 2025). A tumor composed of atypical neoplastic, often pleomorphic cells that invade other tissues. "LHX6 inhibits tumorigenesis and progression in multiple cancers by regulating various pathways or genes which were involved in proliferation, apoptosis, migration, and cell cycle." (PMID 37378426, 2023). "LIM homeobox 6 (LHX6) has been reported to be downregulated and inhibits cell proliferation in various cancers." (PMID 35384355, 2022). "LHX6 mRNA, a member of the LHX6 gene family, encodes a LIM homeodomain transcription factor and can act as a novel cancer biomarker and therapeutic target." (PMID 31810245, 2019). "For example, our data demonstrate that miR-21 and miR-155 are related with progression and invasion of GBM by regulating marker genes of cancer metastasis, such as LHX6, DRD1, NEUROG1 and RAB27B, and thereby contributing to GBM patient survival." (PMID 29312626, 2017). "LHX6 is downregulated in various cancers and inhibits cell proliferation, invasion, and migration." (PMID 35384355, 2022).
LHX6 also shares sentences with these, for which no sentence is quoted: head and neck squamous cell carcinoma (3 papers); Bladder cancer (2); colorectal cancer (2); Epithelial Ovarian Cancer (2); esophageal cancer (2); esophageal squamous cell carcinoma (2); glioma (2); prostate carcinoma (2); acute lymphoblastic leukemia (1); chronic myeloid leukemia (1); clear cell renal cell carcinoma (1); colorectal adenocarcinoma (1); diabetic neuropathy (1); follicular lymphoma (1); glioblastoma (1); head and neck carcinoma (1); Leigh syndrome (1); Nephroblastoma (1); Neurofibromatosis 1 (1); ovarian cancer (1).